TET2 (tet methylcytosine dioxygenase 2)
Diseases named in the same sentence as TET2 in open-access papers (continued):
Sharing a sentence is not in itself a finding about the gene and the disease.
atherosclerosis (continued). "A recent study has shown that a decrease in TET methylcytosine dioxygenase 2 (TET2) promotes methylation of the Beclin 1 promoter and induces endothelial cell autophagy during the pathogenesis of atherosclerosis." (PMID 33030764, 2020). "According to the report that approximately 10-20% of the population over age 70 had observable clonal hematopoiesis, we expected a decrease of TET2 expression, a higher 5-mC level and a lower 5-hmC level in elderly people with significant atherosclerosis." (PMID 31123222, 2019). "Given that the oxLDL-induced endothelial dysfunction plays a critical role in atherosclerosis, our finding that TET2 can improve the endothelial dysfunction induced by oxLDL will further support an inhibitive effect of TET2 on atherosclerosis." (PMID 28798687, 2017). "TET2 expression was homogeneously present across the vascular wall in atherosclerosis-free arteries." (PMID 27821816, 2016). "In the present study, we investigated the role of TET2 in atherosclerosis and its potential mechanisms." (PMID 27821816, 2016). "To determine the role of TET2 in atherosclerosis, we first analyzed the extent of TET2 in normal vascular tissue and atherosclerotic lesions in ApoE−/− mice." (PMID 27821816, 2016). "Moreover, mice with impaired TET2 in their bone marrow developed more severe atherosclerosis due to their macrophages showing increased expression of pro-inflammatory genes, highlighting the gene’s protective role against CVD by controlling inflammation." (PMID 41458386, 2025). "TET2 deficiency led to altered immune responses and increased plaque formation in mouse models, emphasizing the significant role of epigenetic changes in CHIP and its potential contribution to the pathogenesis of atherosclerosis." (PMID 40244103, 2025). "Therefore, DNMT3A mutations, similar to TET2 and JAK2, link epigenetic regulation of autophagy to macrophage-driven atherosclerosis." (PMID 40244103, 2025). "In a TET-2 mutated CH model, for example, monocyte-macrophages are activated with up-regulation of IL-1β signaling, mediated by the activated NLRP3 inflammasome, accelerating atherosclerosis development and maladaptive cardiac remodeling in mice." (PMID 40355940, 2025). "The results indicated accelerated Tet2−/− clone growth in HSCs and myeloid cells under conditions of an atherogenic diet, suggesting a potential vicious cycle wherein atherosclerosis triggers the development of CH, which, in turn, drives further progression of atherosclerosis." (PMID 39119355, 2024). "Interestingly, Dnmt3a LOF augmented atherosclerosis only when homozygous, in contrast with findings with Tet2 LOF." (PMID 39352379, 2024). "Although the clinical significance of LAB CH in atherosclerosis needs to be further clarified, inflammasome activation is prominent in TET2, JAK2VF, and probably ASXL1 CH, suggesting that common underlying mechanisms may support inflammatory crosstalk." (PMID 39531316, 2024). "Despite different methylation patterns, TET2 or DNMT3A CHIP may both drive atherosclerosis by boosting inflammation." (PMID 39352379, 2024). "Bone marrow transplantation of atherosclerosis-prone mice with TET2-deficient bone marrow resulted in an increase in plaque development, which was associated with increases in NLRP3-mediated IL-1β production in TET2-deficient macrophages." (PMID 36613465, 2022). "Indeed, the deleterious effect of TET2 knockdown can be reversed by treatment with the NLRP3 inhibitor MCC950, indicating the pivotal role of IL-1β/NLRP3 inflammasome in TET2 atherosclerosis-related signaling." (PMID 35663390, 2022).
atherosclerosis (continued). "In parallel, other groups have shown that depletion of TET2 might accelerate atherosclerosis due to dysfunctional autophagy, as a major AMPK-regulated pathway." (PMID 36355225, 2022). "More recently, two landmark studies have independently demonstrated the important role of the hematopoietic DNA demethylating enzyme TET2 in preventing atherosclerosis by repressing pro-inflammatory cytokine and chemokine expression as well as inflammasome activation." (PMID 34419168, 2021). "Previous studies showed that TET2 was downregulated during the pathogenesis of atherosclerosis." (PMID 34100182, 2021). "Inhibition of TET2 upregulates the production of mature proinflammatory cytokines including IL-1β and IL-18, which activates the inflammation response and subsequently contributes to and accelerates atherosclerosis." (PMID 33085059, 2021). "Authors observed a clonal expansion into all blood cell lineages, and, regardless the type of diet, a profound effect on diet-induced atherosclerosis in Tet2 KO mice that displayed plaques in the aortic root which were 60% larger than those in wild-type controls." (PMID 32748835, 2020). "More specific approaches to affect the interaction between clonal hematopoietic cells and the development of atherosclerosis could be represented an anti-inflammatory treatment affecting IL-1β or the restoration of TET2 function by vitamin C." (PMID 32825226, 2020). "TET2 levels are inversely correlated with the severity of atherosclerosis." (PMID 28798687, 2017). "Our previous studies have found that TET2 inhibits atherosclerosis in ApoE knockout mice." (PMID 28798687, 2017). "Recent studies have shown that TET2 affects atherosclerosis progression." (PMID 28798687, 2017). "Our findings not only provide a new perspective on the regulation of endogenous CSE/H2S system but also reveal a novel role for TET2 in the protection of endothelial functions, suggesting that TET2 may become a new drug target for treating atherosclerosis." (PMID 28798687, 2017). "Accordingly, this study determined the role of TET2 in atherosclerosis and potential mechanisms." (PMID 27821816, 2016). "Overall, we identified that TET2 was downregulated during the pathogenesis of atherosclerosis." (PMID 27821816, 2016). "Mutations in genes such as ten-eleven translocation-2 (TET2), Janus kinase 2 (JAK2), and DNA methyltransferase 3 alpha (DNMT3A), which are frequently observed in patients with CH, have been shown to promote inflammatory responses and alter macrophage function in the context of atherosclerosis." (PMID 40244103, 2025). "In summary, atherosclerosis and CHIP form a self-perpetuating cycle in which inflammation drives HSC proliferation and mutation accumulation, while mutant clones, particularly those with TET2 and DNMT3A alterations, boost pro-inflammatory signaling and accelerate vascular dysregulation." (PMID 41516113, 2025). "Notably, a variant of TET2 was identified as being more prevalent in individuals of African ancestry, suggesting that genetic diversity may influence the impact of CHIP on atherosclerosis risk." (PMID 40244103, 2025). "While other CHIP driver mutations, including TET2, associate with adverse cardiovascular outcomes among individuals with prevalent atherosclerosis, DNMT3A seems not to confer the same risk, although some studies did show a weak association with elevated incident coronary heart disease." (PMID 39352379, 2024). "It is unknown whether patients with atherosclerosis (or PAH) should be screened for TET2 mutations, particularly as canakinumab is not currently approved for either indication." (PMID 37947606, 2023). "In contrast, monocyte-function appeared to remain mainly stable in the presence of TET2 mutations, with the exception of the promotion of macrophage migration inhibitory factor (MIF), a pivotal factor for monocytic differentiation, that is characteristically elevated in atherosclerosis." (PMID 36355225, 2022).
atherosclerosis (continued). "However, the specific molecular mechanism of TET-2 in the pathogenesis of atherosclerosis remains unclear, requiring further experimental confirmation." (PMID 35965615, 2022). "While this finding does not support a major role of TET2 loss in atherosclerosis, it is equally important to note that molecular characters of CH cells that have accumulated additional changes during somatic selection may be more aggressive and atherogenic." (PMID 30890702, 2019). "In addition, a recent study established a causal link between NLRP3-mediated overproduction of IL-1β and the development of atherosclerosis in a ten-eleven translocation 2 (TET2) mutant mouse model, which could be abrogated by an NLRP3 inflammasome inhibitor." (PMID 30279971, 2018). "Therefore, TET2 might protect cells from inflammation by improving autophagy and direct anti-inflammation effect, suggesting that TET2 overexpression is an attractive strategy to treat atherosclerosis." (PMID 27821816, 2016). "Upregulation of TET2 may be a novel therapeutic strategy for treating atherosclerosis." (PMID 27821816, 2016). "In contrast to TET2 and DNMT3A, where NLRP3 inflammasome activation appears predominant as a mechanism that drives accelerated atherosclerosis, recent data suggest that ASXL1 and JAK2 CHIP provoke activation of the AIM2 inflammasome." (PMID 39352379, 2024). "In murine models of CHIP driven by Tet2, NLRP3 inhibitor MCC950 reduces IL-1β and atherosclerosis, and decreases fibrosis and hypertrophy following myocardial infarction." (PMID 32748835, 2020). "Furthermore, the relationship between ASXL1 mutations and inflammation or atherosclerosis remains poorly understood, though it is hypothesized that the myeloid bias seen in ASXL1 CHIP carriers may produce effects similar to those seen with TET2 loss-of-function mutations." (PMID 39997650, 2025). "Our findings provide insight into the interplay between epigenetic modulators and transcription factor activity in hematological neoplasia, but do not confirm the putative role of TET2 in atherosclerosis." (PMID 30890702, 2019). "Ten-eleven translocation-2 (TET2) protein is a DNA demethylase that regulates gene expression through DNA demethylation and also plays important roles in various diseases including atherosclerosis." (PMID 28798687, 2017). "In sum, our findings have suggested that the anti-atherosclerotic effect of TET2 may be mediated by the CSE/H2S system, but more in vivo studies will be required to establish the role of the TET2/CSE/H2S pathway in atherosclerosis." (PMID 28798687, 2017). "Proteomic profiling of atherosclerotic plaques from TET2 CHIP carriers in the MISSION Biobank revealed enrichment of pathways related to lipid metabolism and inflammation, suggesting a mechanistic link between epigenetic dysregulation and accelerated atherosclerosis." (PMID 40900105, 2026). "TET2, through its role in DNA demethylation, potentially influences the expression of important vascular smooth muscle cell genes such as myocardin (MYOCD) and serum response factor (SRF), which are crucial for smooth muscle function and differentiation in atherosclerosis." (PMID 40428388, 2025).
atherosclerosis (continued). "In addition, TET2 may affect the regulation of KLF4, a gene involved in phenotypic switching of vascular smooth muscle cells, a process central to the pathology of atherosclerosis." (PMID 40428388, 2025).
chronic myelomonocytic leukemia (89 papers, 2011 to 2025). A myelodysplastic/myeloproliferative neoplasm which is characterized by persistent monocytosis, absence of a Philadelphia chromosome and BCR/ABL fusion gene, fewer than 20 percent blasts in the bone marrow and blood, myelodysplasia, and absence of PDGFRA or PDGFRB rearrangement. "The mutation rates for DNMT3A and TET2 in either gene or both were as high as 92.9% in angioimmunoblastic T cell lymphoma, 80% in chronic myelomonocytic leukemia, 58.4% AML with mutated NPM1 and 57.1% in peripheral T cell lymphoma." (PMID 34039392, 2021). "Somatic TET2 mutations are present in approximately 50% of chronic myelomonocytic leukemia (CMML; an MDS/MPN) cases, ~30% of MDS, and ~10% of AML." (PMID 31963585, 2020). "TET2 is another epigenetic modifier which is frequently mutated in hematological malignancies, including chronic myelomonocytic leukemia (CMML), MDS/myeloproliferative neoplasms (MPNs), AML, and T- or B-cell lymphoma." (PMID 31527484, 2019). "In patients who develop chronic myelomonocytic leukemia and carry TET2 mutations in CD34+ hematopoietic progenitor cells, the TET2-mutated CD34+ progenitors preferentially develop into myeloid instead of erythroid cells upon differentiation." (PMID 30290828, 2018). "In MDS, TET2 mutations are found in 20%–25% of patients, but occur at a higher frequency of 30%–60% in chronic myelomonocytic leukemia (CMML)." (PMID 27023522, 2016). "As reported by our previous studies among others, Tet2 mutation is a well-known inducer of clonal hematopoiesis and may lead to chronic myelomonocytic leukemia–like diseases in aged mice." (PMID 39537342, 2025). "Mono- or bi-allelic somatic mutations along the entire coding TET2 region are recurrent events in human hematopoietic malignancies, especially in chronic myelomonocytic leukemia (CMML) in which mono- or bi-allelic mutations in TET2 gene are detected in 57% of patients." (PMID 35115654, 2022). "In MPN01, a differential mutation repartition with preferential expansion of the TET2-mutated clone towards the monocytic population was observed, a known phenomenon described for TET2-mutated HSCs in chronic myelomonocytic leukemia (CMML) and clonal hematopoiesis." (PMID 31911629, 2020). "Specifically, single and multiple TET2 mutations were analyzed separately, hypothesizing the presence of a distinct signature derived from the gene dosage effect of TET2 as was observed in chronic myelomonocytic leukemia." (PMID 40164718, 2025). "A study among Hispanics from Puerto Rico living in California, diagnosed from 2009 to 2018 with chronic myelomonocytic leukemia (CMML), found a higher rate of mutated TET2 and wild ASXL1." (PMID 37196029, 2023). "Somatic mutation in TET2 gene is one of the most common clonal genetic events detected in age-related clonal hematopoiesis as well as in chronic myelomonocytic leukemia (CMML)." (PMID 35115654, 2022). "TET2 mutations are frequently observed in hematological cancers, like myeloproliferative neoplasms (MPNs), chronic myelomonocytic leukemia (CMML), DLBCL, and AML." (PMID 36059621, 2022). "The TET2 gene is frequently mutated in malignant blood diseases (about ~50% in chronic myelomonocytic leukemia, CMML)." (PMID 35327610, 2022). "Chronic myelomonocytic leukemia (CMML) likely develops from early clones with TET2 mutations that drive granulomonocytic differentiation." (PMID 35844680, 2021). "A high prevalence of TET2 mutations was described in patients with chronic myelomonocytic leukemia (CMML), AML, MPD, and MDS." (PMID 30627525, 2018). "Chronic myelomonocytic leukemia (CMML) has recently been associated with a high incidence of diverse mutations in genes such as TET2 or EZH2 that are implicated in epigenetic mechanisms." (PMID 22328940, 2012). "TET2 variants often represent an early event in the development of human myeloid malignancies, including AML, MDS, MPNs, and chronic myelomonocytic leukemia (CMML), as well as B- and T-cell neoplasms." (PMID 39626264, 2025).